HDAC6 (histone deacetylase 6)
Diseases named in the same sentence as HDAC6 in open-access papers (continued):
Sharing a sentence is not in itself a finding about the gene and the disease.
metastatic prostate carcinoma (1 paper, 2021). A carcinoma that arises from the prostate gland and has spread to other anatomic sites. "p62 was confirmed to inhibit autophagy flux and promote epithelial-mesenchymal transformation in metastatic prostate cancer by maintaining the level of HDAC6." (PMID 34691238, 2021).
microcephaly (1 paper, 2025). A congenital or acquired developmental disorder in which the circumference of the head is smaller than normal for the person's age and sex. "In summary, these findings demonstrate that in zebrafish, targeting Hdac6, either through genetic manipulation or pharmacological modulation, can rescue CITK-dependent microcephaly phenotype." (PMID 40254670, 2025).
minimal changed disease (1 paper, 2022). "Compared to minimal changed disease (MCD) with mild tubular injury, the immunohistochemistry (IHC) staining results showed that renal tubular expression of HDAC6 was significantly increased in the early stage of DN and decreased slightly in the late stage of DN." (PMID 35910382, 2022).
monocytic leukemia (1 paper, 2025). "However, in the U937 human monocytic leukemia cell line overexpressing Pyrin, HDAC6 is not required for IL-18 secretion and cell death in response to the Pyrin activator and bile acid derivative BAA473, suggesting that the role of HDAC6 in Pyrin activation may be cell-type- and trigger specific." (PMID 41062723, 2025).
myeloproliferative neoplasm (1 paper, 2022). A clonal hematopoietic stem cell disorder, characterized by proliferation in the bone marrow of one or more of the myeloid (i.e., granulocytic, erythroid, megakaryocytic, and mast cell) lineages. "Consequently, pharmacological inhibition of HDAC6 could represent an interesting therapeutic strategy in the treatment of myeloproliferative neoplasms, such as polycythemia vera (PV), characterized by the activating mutation JAK2V617F." (PMID 36077192, 2022). "Indeed, recent data have shown that in leukemic cells carrying the JAK2V617F mutation and in murine models of myeloproliferative neoplasms induced by the MPLW515L mutation, HDAC11 more than HDAC6 was required for cell proliferation and survival via the control of the JAK-STAT pathway." (PMID 36077192, 2022).
Nephropathy (1 paper, 2022). A nonspecific term referring to disease or damage of the kidneys. "HDAC6 activation has been reported in cisplatin- and rhabdomyolysis-induced nephropathy in previous studies, and inhibition of HDAC6 alleviated renal damage in these models." (PMID 36552715, 2022).
ocular toxoplasmosis (1 paper, 2026). Ocular toxoplasmosis is an infection in the eye caused by the parasite, Toxoplasm a gondii. "In this study, the HDAC6 inhibitor Tubastatin A was evaluated by intravitreal injection in the murine ocular toxoplasmosis model." (PMID 41533437, 2026).
ovarian endometriosis (1 paper, 2025). A non-neoplastic disorder characterized by the growth of endometrial tissue in the ovaries. "In ARID1A-deficient individuals, epithelial HDAC6 expression was profoundly upregulated in endometriotic lesions compared to control endometria (p = 0.031), particularly in ovarian endometriosis (p = 0.037)." (PMID 40364006, 2025).
ovarian tumors (1 paper, 2020). "A meta-analysis of the correlation between HDAC6 gene expression and survival was performed on 3573 ovarian tumors from 19 datasets showed that high HDAC6 gene expression was associated with a decreased risk of death." (PMID 33322608, 2020).
Pain (1 paper, 2022). An unpleasant sensory and emotional experience associated with actual or potential tissue damage, or described in terms of such damage. "Histone deacetylase 6 (HDAC6) inhibitors have therapeutic potential for cisplatin-induced neuropathic pain since they persistently reverse mechanical hypersensitivity and spontaneous pain in rodent models." (PMID 36096670, 2022).
periodontal disease (1 paper, 2022). "HDAC6 expression was upregulated in the gingival tissues of patients with periodontal disease." (PMID 36444635, 2022).
peritonitis (1 paper, 2020). Inflammation of the peritoneum (tissue that lines the abdominal wall and covers most of the organs in the abdomen). "Taken together, these results indicate that HDAC6 represents abnormal high expression which is associated with peritonitis and long-term exposure injury by traditional high glucose peritoneal dialysate." (PMID 32862739, 2020). "Our study revealed that HDAC6 expressed highly in the peritoneum with peritonitis and co-stained with α-smooth muscle actin (α-SMA), a biomarker of the myofibroblast." (PMID 32862739, 2020). "We found that HDAC6 was highly expressed in the peritoneum from patients with PD-related peritonitis and the dialysis effluent of PD patients." (PMID 32862739, 2020). "While the peritoneum from PD-related peritonitis patients showed a high expression of HDAC6 which were co-expressed with α-SMA-positive cells." (PMID 32862739, 2020). "In this study, we analyzed the expression of HDAC6 in the peritoneum from patients with non-PD and PD-related peritonitis and dialysis effluent from stable PD patients." (PMID 32862739, 2020).
premature ovarian failure (1 paper, 2024). "HDAC6 expression decreases with reproductive aging in the naturally aging mouse model, cisplatin-induced premature ovarian failure (POF) model, human ovarian granulosa cell model with diminished ovarian reserve (POF), and cisplatin-treated human ovarian granulosa cell model." (PMID 38646645, 2024).
prion disease (1 paper, 2022). A transmissible disease that is caused by a protein that is able to induce abnormal folding of normal cellular proteins, leading to characteristic spongiform brain changes, which are associated with neuronal loss without an inflammatory response. "Interestingly, among all the HDACs, the enzyme HDAC6 is involved in both prion diseases and prion-like diseases, although the mechanism of action is different between the two groups of diseases." (PMID 36293477, 2022).
psoriasis (1 paper, 2025). An autoimmune condition characterized by red, well-delineated plaques with silvery scales that are usually on the extensor surfaces and scalp. "Collectively, these results indicate that CS1 is a novel HDAC6 inhibitor, suggesting HDAC6 as a potential target for the treatment of psoriasis-like inflammation." (PMID 40807399, 2025).
renal dysfunction (1 paper, 2019). "In the study, glycerol-injected mice developed severe AKI symptoms as indicated by acute renal dysfunction and pathological changes, accompanied by the overexpression of HDAC6 in tubular epithelial cells." (PMID 31639165, 2019).
respiratory infection (1 paper, 2026). "muridarum respiratory infection upregulates HDAC6 expression at the infection site and in immune organs." (PMID 41977198, 2026). "muridarum respiratory infection and suggest targeted modulation of HDAC6 as a novel therapeutic strategy for chlamydial respiratory infection." (PMID 41977198, 2026).
retinal ciliopathies (1 paper, 2025). "Clinically, the role of HDAC6 is particularly significant in diseases where ciliary dysfunction is a key factor, such as retinal ciliopathies (e.g., RP), renal ciliopathies (e.g., PKD), and respiratory ciliopathies (e.g., COPD)." (PMID 40167251, 2025).
retinoblastoma (1 paper, 2025). A malignant tumor that originates in the nuclear layer of the retina. "Preclinical studies in retinoblastoma models have also shown encouraging results: the HDAC6 inhibitor WT161 induces apoptosis and sensitizes tumor cells to cisplatin, whereas intravitreal belinostat effectively eradicates vitreous seeds with minimal retinal toxicity." (PMID 41150792, 2025).
Right ventricular hypertrophy (1 paper, 2017). In this case the right ventricle is more muscular than normal, causing a characteristic boot-shaped (coeur-en-sabot) appearance as seen on anterior- posterior chest x-rays. "Although not statistically significant, inhibition of HDAC6 tends to result in an increase in cardiac output (CO) and a decrease in right ventricular hypertrophy measured by Fulton index." (PMID 28674407, 2017).
septic shock (1 paper, 2020). Shock caused by infection; frequently caused by gram negative bacteria, although some cases have been caused by other bacteria, viruses, fungi, and protozoa; characterized by fever, chills, tachycardia, tachypnea, and hypotension. "HDAC6 inhibition could be a new therapeutic approach to control NO level and nitrative stress during septic shock, which could improve vascular responses and alleviate tissue injury in septic shock." (PMID 32973784, 2020).
serous carcinoma (1 paper, 2022). "A high level of HDAC6 predicted low progression-free survival (p = 0.001) and overall survival (p = 0.008) in patients with serous carcinoma." (PMID 36076996, 2022). "The PD-L1 level showed a positive correlation with the HDAC6 level in serous carcinoma." (PMID 36076996, 2022).
silicosis (1 paper, 2016). Silicosis is a respiratory disease caused by breathing in (inhaling) silica dust. "In the rat lung, silicosis nodules had increased expression of HDAC6 and HSP90." (PMID 27577858, 2016). "In vivo and in vitro, the expression of HDAC6 and HSP90 was up-regulated in the silicosis group and in fibroblasts induced by Ang II." (PMID 27577858, 2016). "Furthermore, we observed the expression and localization of HDAC6 and HSP90 in rats with silicosis." (PMID 27577858, 2016).
sinusitis (1 paper, 2017). An acute or chronic inflammatory process affecting the mucous membranes of any sinus cavity. "In the present study, HDAC1 was upregulated in the nasal epithelium of NPs, and HDAC6 was upregulated in sinusitis." (PMID 28883651, 2017). "We performed immunohistochemical analysis for HDAC1 and HDAC6 in normal, sinusitis and NP tissues." (PMID 28883651, 2017). "The immunohistochemical results showed that HDAC1 was upregulated in the nasal epithelium of the sinusitis and NPs, and HDAC6 was upregulated in the sinusitis, whereas HDAC1 and HDAC6 were positive in the normal nuclei." (PMID 28883651, 2017). "In the present study, p63, ΔNp63, HDAC1 and HDAC6 were upregulated and CLDN-1 and -4 were downregulated in the epithelium of sinusitis and NPs." (PMID 28883651, 2017).
skin cutaneous melanoma (1 paper, 2024). "Lastly, we evaluated the correlation between HDAC6 expression and SIRPα expression in skin cutaneous melanoma (SKCM) patients utilizing Gene Expression Profiling Interactive Analysis (GEPIA), a server for interactive analysis of normal and cancer expression profiles." (PMID 38414061, 2024).
small fiber neuropathy (1 paper, 2025). "Nonetheless, these studies consistently demonstrated that HDAC6 inhibitors alleviate small fiber neuropathy and neuropathic pain, as evidenced by behavioral assessments and IENF density measurements." (PMID 41012388, 2025).
T-cell neoplasms (1 paper, 2023). "More importantly, a selective HDAC6 inhibitor (KT-531) impaired the viability of T-PLL cells, and in contrast to pan-HDACi, had little to no activity in other T-cell neoplasms." (PMID 37569479, 2023).
T-cell prolymphocytic leukemia (1 paper, 2025). A slow-growing type of leukemia (blood cancer) in which too many lymphocytes are found in the bone marrow and/or blood. "In another study, an HDAC6-selective inhibitor, St.17, was developed through a SAR approach for the treatment of T-cell prolymphocytic leukemia (T-PLL), an aggressive and currently incurable hematological malignancy." (PMID 41440016, 2025).
thymic epithelial tumors (1 paper, 2023). "In this study we attempt the first comprehensive evaluation of six class I (HDAC1, HDAC2, HDAC3) and II HDACs (HDAC4, HDAC5, HDAC6) expression patterns in thymic epithelial tumors (TETs), with the aim of identifying their possible association with a number of clinicopathological parameters." (PMID 36901692, 2023).
thyroid tumor (1 paper, 2015). A benign or malignant neoplasm affecting the thyroid gland. "In conclusion, our studies brought new evidence of ROCK/HDAC6 pathway involvement in thyroid tumors aggressiveness." (PMID 26415230, 2015).
tongue SCC (1 paper, 2024). "In tongue SCC cells CAL-27 (ATTC, CRL2095) and SCC-9 (ATCC, CRL-1629) that are CDDP-resistant, the authors found elevated levels of HDAC6 as well as its nuclear accumulation." (PMID 39272862, 2024).
tuberculosis (1 paper, 2023). A chronic, recurrent infection caused by the bacterium Mycobacterium tuberculosis. "HDAC6 may be a risk factor for tuberculosis (TB) and a novel host-directed anti-TB therapeutic target." (PMID 37638049, 2023).
Type 1 diabetes (1 paper, 2020). "Using an interventional approach, we assessed the effects of pharmacological inhibition of HDAC6 by administration of the specific inhibitor TS in an experimental model of Type 1 diabetes (STZ-rats)." (PMID 32660051, 2020).
type 2 diabetic nephropathy (1 paper, 2020). "However, the role of HDAC6 in type 2 diabetic nephropathy (DN) remains undefined." (PMID 32885602, 2020).
cancer (357 papers, 2008 to 2026). A tumor composed of atypical neoplastic, often pleomorphic cells that invade other tissues. "In order to explain differences in an activity level, molecular modelling supported by molecular dynamics was performed on histone deacetylase 6 (HDAC6), a known therapeutic target associated with oncogenic transformation and cancer metastasis." (PMID 41751392, 2026). "An integrated analysis of cancer patient datasets for HDAC6-activity-affected gene expression profiles indicated that the UPR is the primary pathway associated with HDAC6 activity in cancer." (PMID 39941046, 2025). "Here they show that HDAC6 inhibition regulates fumarate hydratase (FH), disrupts mitochondria, increases fumarate, and causes cancer cell death." (PMID 40721560, 2025). "Research has shown that HDAC6 overexpression has been linked to various cancers, including hepatocellular carcinoma, glioblastoma, and prostate cancer." (PMID 37461108, 2023). "The high expression of HDAC6 was identified in breast, renal, lung, and endometrial cancers, and its upregulation in cancers was strongly associated with a poor overall survival rate." (PMID 36639650, 2023). "HDAC6, like other HDACs, is a promising pharmacological target also in the context of efforts to combat diseases other than cancer, especially those associated with inflammation." (PMID 37626935, 2023). "Dysregulation ofboth tubulin deacetylases sirtuin 2(Sirt2) andthe histone deacetylase 6 (HDAC6) has been associated with the pathogenesisof cancer and neurodegeneration, thus making these two enzymes promisingtargets for pharmaceutical intervention." (PMID 37902787, 2023). "Th abnormal expression of HDAC6 is associated with cancer development, disease progression, a higher incidence of metastasis and lower survival rates." (PMID 36986673, 2023). "HDAC6 plays significant roles in multiple processes associated with tumorigenesis, including increased cellular proliferation, migration, and invasion of cancer cells." (PMID 37446224, 2023). "Based on the combined score of each interaction with 0.4 confidence, the top 3 significant cancer-related signaling pathways in association with HDAC6 were Akt1 (0.704), MAPK1 (0.584), and TNF (0.403)." (PMID 36639650, 2023). "Perversely, high or low HDAC6 expression levels are associated with disease pathogenesis in different cancers." (PMID 36012642, 2022). "Aberrant HDAC6 activity has been associated with cancer progression, neurodegenerative diseases, and inflammatory disorders." (PMID 36355493, 2022). "In the present study, we found that HDAC6 expression was strongly associated with mutation levels in five MMR genes in human pan-cancers, but there were some exceptions in tumors (READ and UCS)." (PMID 34485153, 2021). "Despite the flaws of the current study, we have to acknowledge the close association of HDAC6 in tumor immunity and cancer development." (PMID 34485153, 2021). "In the present study, we determined that HDAC6 was differentially expressed in pan-cancers and that abnormal expression was associated with tumor progression, especially in COAD." (PMID 34485153, 2021). "These proteins are involved in multiple cell functions, and deregulation of HDAC6 activity is associated with a variety of diseases, including cancer." (PMID 34345016, 2021). "From a clinical point of view, HDAC6 overexpression in many tumor types is associated with poor prognosis, drug resistance, cancer cell proliferation and migration." (PMID 34345016, 2021). "Dysregulation of HDAC6’s deacetylase activity and HDAC6 overexpression have both been associated with cancer and cisplatin resistance." (PMID 32382008, 2020).